CDH2 (cadherin 2)
Diseases named in the same sentence as CDH2 in open-access papers (continued):
Sharing a sentence is not in itself a finding about the gene and the disease.
obsessive-compulsive disorder (1 paper, 2020). A disorder characterized by the presence of persistent and recurrent irrational thoughts (obsessions), resulting in marked anxiety and repetitive excessive behaviors (compulsions) as a way to try to decrease that anxiety. "Polymorphisms in CDH2 have been associated with canine obsessive-compulsive disorder." (PMID 33167491, 2020).
Osteopenia (1 paper, 2015). Osteopenia is a term to define bone density that is not normal but also not as low as osteoporosis. "Additionally, osteoblast- and osteocyte-specific conditional knockout of Cdh2 (N-cadherin) and double Cdh2+/−; Cdh11−/− mutation reportedly lead to osteopenia in adult mice." (PMID 25759206, 2015).
ovarian serous cystadenocarcinoma (1 paper, 2022). A malignant serous cystic epithelial neoplasm arising from the ovary. "The positive correlation between HK2 and CDH2, fibronectin, MMP9, ZEB1, ZEB2 and vimentin in OV (ovarian serous cystadenocarcinoma) was confirmed by using TIMER 2.0." (PMID 35953860, 2022).
rectum cancer (1 paper, 2021). "Meanwhile, based on combined Kaplan–Meier curves with log-rank p test, CDH2 was obviously associated with overall survival (OS; p<0.01) and disease-free survival (DFS; p<0.01) in CRC, with a particularly strong associated observed for rectum cancer." (PMID 34422629, 2021).
spina bifida (1 paper, 2023). A congenital neural tube defect in which vertebrae are not fully formed. "Together, these results indicate that in the background of Vangl2Lp/+, the occurrence of spina bifida due to the heterozygosity of Cdh2 was not evoked by changes in the signal strength of the RhoA-Mypt1 or JNK-Jun pathways." (PMID 36890135, 2023).
steatosis (1 paper, 2025). Increased lipid within the cytoplasm of cells. "The strongest association with steatosis degree was for CDH2 plasma abundances." (PMID 39017916, 2025). "The study identified five circulating proteins associated with the steatosis grade in the liver: Cathepsin O (CTSO), Cadherin 2 (CDH2), Leukocyte immunoglobulin-like receptor subfamily A member 5 (LILRA5), and Serpin B6 (SERPINB6); and Prolyl endopeptidase (FAP)." (PMID 39017916, 2025). "Moreover, among the proteins showing changes in their expression with steatosis, we observed CDH2 (ρ = 0.52, p < 0.001), CTSO (ρ = 0.44, p < 0.001), and LLRA5 (ρ = 0.45, p < 0.001) presenting the most significant correlations." (PMID 39017916, 2025). "The candidates to be combined in future algorithms for steatosis are CTSO, CDH2, LILRA5, SERPINB6, and FAP." (PMID 39017916, 2025). "Five circulating proteins, including Cathepsin O (CTSO), Cadherin 2 (CDH2), and Prolyl endopeptidase (FAP), were identified as biomarkers for steatosis." (PMID 39017916, 2025). "CDH2, CTSO, Leukocyte Immunoglobulin Like Receptor A5 (LILRA5), BMI, waist circumference, HOMA-IR, and FLI, among others, significantly correlated with the steatosis degree." (PMID 39017916, 2025).
vitamin A deficiency (1 paper, 2024). Deficiency of vitamin A due to malnutrition, malabsorption, or dietary lack. "Indeed, there was an EMT switch: Cdh1 decreased in the lungs after vitamin A deficiency (VAD) whilst Cdh2 levels increased statistically." (PMID 38674868, 2024).
vitiligo (1 paper, 2024). Generalized well circumscribed patches of leukoderma that are generally distributed over symmetric body locations and is due to autoimmune destruction of melanocytes. "It was found that the expression of Wnt pathway components such as LEF1, CDH2, and CDH3 was downregulated in the lesional skin of vitiligo." (PMID 38361944, 2024). "In addition, it was found that the expression of Wnt pathway components such as LEF1, CDH2, and CDH3 was downregulated in the lesional skin of vitiligo." (PMID 38361944, 2024).
Zinc deficiency (1 paper, 2025). A deficiency of the essential metal Zinc; an essential cofactor for many enzymes. "Specifically, our findings demonstrate that zinc deficiency significantly upregulates the expression of CDH2, Vimentin, and Snail in renal tissues while downregulating CDH1." (PMID 39028478, 2025). "The levels of CDH2, Vimentin, and SNAIL were significantly downregulated compared with the zinc deficiency group, while CDH1 expression was restored." (PMID 39028478, 2025).
tumor (1,831 papers, 1995 to 2026). "In NSCLC, the downregulation or loss of CDH1 and upregulation of CDH2 is frequently observed and is associated with increased invasiveness and the ability of tumor cells to detach from the primary tumor site." (PMID 40860670, 2025). "Experimental and clinical studies have further demonstrated the gatekeeper role of epithelial-to-mesenchymal transition (EMT) in modulating tumor invasion and metastasis, where CDH2 and VIM have been underlined to be involved." (PMID 39735560, 2024). "LUAD patients with high CDH2 expression in tumor-derived endothelial cells are significantly associated with an unfavorable prognosis, tumor stage and visceral pleural metastasis." (PMID 34880371, 2021). "Consistent with these previous studies, we found the expression of CDH2 was higher in MPM tumor tissues than normal tissues and the high expression level of CDH2 was associated with poor prognosis." (PMID 32849853, 2020). "Additional analyses revealed that rs643555T was associated with higher expression of CDH2, and upregulated CDH2 was correlated with tumor aggressiveness and shortened BCR‐free survival." (PMID 30993852, 2019). "Total EMT (loss of CDH1 expression associated with overexpression of CDH2) was observed in only one tumor in the present study." (PMID 29845746, 2018). "Likewise, high ZEB1 or high CDH2 protein levels in the tumor cells (MART-1+) were associated with a worse prognosis." (PMID 41429767, 2025). "All these four prognostic genes were significant associated with dendritic cell Tumor immune infiltration abundance: CDH2 (r = 0.296, P = 5.84 × 10−9), CDH6 (r = 0.164, P = 1.49 × 10−3), CDH6 (r = − 0.105, P = 4.41 × 10−2) and CDH10 (r = 0.274, P = 7.78 × 10−8)." (PMID 34880371, 2021). "Moreover, high CDH2 expression in TECs was significantly associated with tumor stage, visceral pleural metastasis, and decreased overall survival in patients with ADC but not SCC." (PMID 30832661, 2019). "This study demonstrates that CDH1, CDH2, and CDH3 are significantly upregulated in NSCLC and are associated with tumor progression, poor prognosis, and advanced disease stages." (PMID 40860670, 2025). "CDH2, a member of the calreticulin family, plays a crucial role in driving malignant phenotypes in tumor cells by promoting intercellular adhesion and activating downstream signaling pathways, such as EMT." (PMID 40689207, 2025). "CCL26high OSCC had a characteristic of tumor invasive phenotype with upregulated CLDN8/20 and reduced keratin KRT36, which was significantly associated with EMT markers (CDH1, CDH2, VIM, SNAI2)." (PMID 39931245, 2025). "Untreated PDXs showed high Ki67 indices but did not reproduce the conspicuous stromal invasion of CDH1low/SNAI2+/CDH2+ cells that characterized the primary tumor." (PMID 40600748, 2025). "In many cancer types, both E-cadherin (CDH1) and N-cadherin (CDH2) contribute to tumor behavior, though their functions can diverge depending on tumor type, microenvironment, and disease stage." (PMID 40860670, 2025). "In this context, N-cadherin (CDH2) is frequently overexpressed in neoplastic cells and has been implicated in facilitating tumor progression." (PMID 41295661, 2025). "Mesenchymal marker CDH2 also follows this trend, showing lower expression in poor prognosis tumours (log2fc = 0.51)." (PMID 41007296, 2025). "Cadherin E (CDH1) and cadherin N (CDH2) are significant contributors to tumor development: a form of metaplasia known as epithelial–mesenchymal transition (EMT)." (PMID 39061990, 2024). "CDH2 and its altered neighboring genes (ANGs) mainly affect tumor-related gene expression, cell cycle, and energy metabolism." (PMID 39545598, 2024). "Consistently, exposure to Eo33-EV also induced up-regulation of Cdh1 and down-regulation of Cdh2 in tumor cells." (PMID 39061080, 2024). "We found that tumor samples that overexpressed the MET genes (CDH2 and TGF genes) had a decreased survival probability in relation to the overall mean expression of those genes." (PMID 38539520, 2024).
tumor (continued). "Other cell type‐specific markers were similarly detected in the primary tumours (CDH2, CD3D and CD79A), including a notably low detection of CD19 in B cell populations." (PMID 37691350, 2023). "CDH2, SPP1, and TNC maintained a statistically significant increase associated with the progression of individual cancer stages in LUAD tumor samples compared to their respective controls." (PMID 37887075, 2023). "On the other hand, the results showed that, for LUSC tumor samples, CDH2, SPP1, and TNC were significantly upregulated and FN1, CYR61, SERPINA1, and IL6 were significantly downregulated compared to their respective controls." (PMID 37887075, 2023). "On the one hand, the tumor hybrids expressed “classical” M-genes, such as CDH2 and VIM, suggesting that they are rather in a M state." (PMID 38139138, 2023). "In adenocarcinoma, miR-9-5p exerts a tumour suppressive role and the epithelial-to-mesenchymal transition phenotype is achieved by low levels of miR-9-5p, which enable the upregulation of CDH2 via the transcription factor TWIST1." (PMID 36961325, 2023). "CDH2 supports tumour growth and promotes microenvironment-mediated treatment protection, decrease cell division rate and potentially plays a role in cancer dormancy." (PMID 37132370, 2023). "For the remaining seven S100P- iCCAs (P09, P10, P12, P13, P14, P15, and P19), they expressed iCCApps markers NCAM1 and CDH2, which were mutually exclusive with the expression of S100P, confirming the different origins of these tumor cells." (PMID 35347134, 2022). "Here, we showed that CDH2 expression levels were significantly higher in tumor tissues than in normal tissues in THCA." (PMID 35756646, 2022). "Vegfa was significantly downregulated in combination with the tumor cell–endothelial cell migration integrin Cdh2." (PMID 35328529, 2022). "The role of CDH2 in directing stem-cell fate, tumor-microenvironment interactions, and chemoresistance has been implicated in a wide variety of solid tumors and certain hematological malignancies such as CML." (PMID 35977468, 2022). "In this study, The mRNA and protein expression levels of FRMD3 were significantly elevated in THCA tissues, implying that FRMD3, similar to CDH2, plays a tumor-promoting function in THCA." (PMID 35756646, 2022). "The lung metastasis capability of Cdh2-KO cells was evaluated by intravenously injecting these tumor cells into the mice." (PMID 35890278, 2022). "Irrespective of CDH1 expression, the migratory and invasive capacities are present in tumor cells by CDH2 expression." (PMID 36315446, 2022). "During epithelial-mesenchymal transition (EMT), tumor cells can transform to a CSC-like phenotype with an increase in CDH2." (PMID 35058980, 2022). "We also used ROC curves to predict tumor and normal outcomes, and the results showed that CDH2 had a certain accuracy in its predictive power (AUC = 0.826, CI = 0.786-0.866)." (PMID 35756646, 2022). "Significantly reduced tumor cell migration was observed in the Cdh2 gene-knockout 4T1 cells in comparison with the wild-type cells." (PMID 35890278, 2022). "Expression of ITGA11 was negatively correlated with CDH1, whereas positively correlated with VIM or CDH2 in tumor samples of STAD from the TCGA and GSE66229 datasets." (PMID 34222028, 2021). "What more, the differentially expressed genes between MTDH-high and MTDH-low tumor samples include EMT-associated genes, such as fibronectin (FN1), N-cadherin (CDH2), and SMAD." (PMID 34622157, 2021). "Cav-1 and Cav-2 were reported to be regulated by FGFR4 and CDH2 and, also, correlated with tumor progression, invasion and metastasis." (PMID 33809909, 2021). "As a member of the cadherin family, CDH2 exists in the nervous system and is also involved in the occurrence and metastasis of tumor cells." (PMID 33860034, 2021).
tumor (continued). "Tumor immune infiltration abundance of macrophage also shown a significantly associated with CDH2 (r = 0.474, P = 3.59 × 10−22), CDH6 (r = 0.418, P = 4.20 × 10−17) and CDH10 (r = 0.492, P = 6.60 × 10−24) in GC tumor tissues." (PMID 34880371, 2021). "As a calcium-dependent cell adhesion protein, CDH2 can mediate homotypic cell-cell adhesion by dimerization with a CDH2 chain from another cell to promote tumor cell metastasis." (PMID 34422629, 2021). "Tumor immune infiltration abundance of neutrophil were closely correlated with CDH2 (r = 0.149, P = 4.10 × 10−3) and CDH10 (r = 0.147, P = 4.54 × 10−3) expression." (PMID 34880371, 2021). "Compared with the primary tumor, in the metastasis group, the mesenchymal markers (CDH2, VIM, TWIST1, SNAI1, ZEB1) and ferroptosis drivers increased, and the epithelial marker CDH1 and ferroptosis suppressor decreased." (PMID 35127731, 2021). "Increased expression of CDH2, CTSB, ACTA2, MMP2 and ZEB1 was associated with increased myometrial invasion, and expression of CTSB and MMP9 was significantly associated with tumor recurrence." (PMID 34936030, 2021). "DSTYK expression is positively proportional to the expression of TGF-β, mesenchymal markers vimentin (VIM) and N-cadherin (CDH2) in tumor tissues from human CRC patients, whereas it is inversely correlated to epithelial marker E-cadherin (CDH1) expression." (PMID 32982725, 2020). "DNER regulates its downstream target RBPJ and SKP1, and also interacts with the important factors of Wnt signaling pathways, CTNNB1 and CDH2, regulating tumor proliferation, differentiation, invasion, migration and angiogenesis of PanNENs tumorigenesis." (PMID 33329729, 2020). "While E-cadherin (coded by CDH1) is considered a tumor repressor, mesenchymal marker N-cadherin (coded by CDH2) is regarded as a tumor facilitator in carcinomas." (PMID 33348918, 2020). "Isolated Met-1 tumor cells from obese mice demonstrated increased expression of epithelial-to-mesenchymal transition marker N-cadherin (Cdh2) compared to those from lean mice, consistent with increased invasive behavior (p = 0.04)." (PMID 32098183, 2020). "This characteristic is typical during the EMT process often occurring in tumor malignancy where, thanks to a switch between Cdh1 and Cdh2, tumor cells loosen cell-cell adhesivity." (PMID 31426573, 2019). "Methylation analysis of the Cdh1, Cdh2, Mmp9, Mki67, Gfap, Gap43, Robo2, and Slit2 genes from tumor samples demonstrated that all of them were methylated in their promoter regions unlike those from normal tissues." (PMID 31921388, 2019). "Strikingly, although Akt1 was not significantly different between the selected cohorts, a trend towards increased TGFβ1, CDH2 (N-cadherin) and Snail were observed in the metastatic tumor sites (N=114) compared to the tumors localized in the prostate (N=4)." (PMID 31360736, 2019). "Here, we found that the transcriptomic profiling of NB-MSCs isolated from tumor samples derived from NB patients was enriched in EMT-associated genes compared to BM-MSCs, in particular in CDH2 and MMP-9 genes." (PMID 30482160, 2018). "In agreement with the transcriptional profile, immunostaining of patient tumor sections showed that CDH1 was only present in the choroidal tissue while CDH2 manifested an opposite pattern." (PMID 28246385, 2017). "A “Cadherin Switch” refers to the change from CDH1 to CDH2 and is considered to be the key factor in tumour invasion and metastasis." (PMID 29115924, 2017). "Validation of selected mRNAs was performed on the same patients cohort by RT-qPCR and, according to the expression profiling results, we evidenced the up-regulation of Golm-1, Psat-1 and CDH2 in tumor tissues compared to normal samples." (PMID 28486946, 2017). "The association of PTEN loss of function with CDH2 upregulation made difficult to find mutant PTEN UBC lines that expressed E-cad (two in the UBC collection; two in the diverse tumor set)." (PMID 27863432, 2016).